VCAM1 (vascular cell adhesion molecule 1)
Diseases named in the same sentence as VCAM1 in open-access papers (continued):
Sharing a sentence is not in itself a finding about the gene and the disease.
keloid (2 papers, 2022 to 2025). An irregularly shaped, elevated mark on the skin caused by deposits of excessive amounts of collagen during wound healing. "For instance, valproic acid is predicted to interact with NTF3, while dexamethasone is associated with VCAM1, suggesting that these genes could serve as potential therapeutic targets for modulating gene activity in the treatment of keloids." (PMID 40051702, 2025). "In the violin plot, EDN1, NTF3, ADRB2, and VCAM1 were found to be significantly upregulated in keloid tissue, with very high statistical significance (***, p < 0.001)." (PMID 40051702, 2025). "The immune cell infiltration and correlation analysis in keloid tissues revealed significant associations between the expression of the hub genes ADRB2, NTF3, VCAM1, EDN1 and various immune cell types." (PMID 40051702, 2025). "Ultimately, 7 hub genes—EDN1, NTF3, VCAM1, ADRB2, BDNF, F3 and FLT1—were identified, all of which had interaction scores above 0.70, indicating their potential roles in keloid formation and progression." (PMID 40051702, 2025). "The heatmap illustrates the differential expression of these 13 OSRDEGs between keloid and normal skin tissues, where F3, FOXL2, EDN1, and NTF3 show higher expression in keloid tissues, while BDNF, FLT1, VCAM1 and ADRB2 are more highly expressed in normal skin." (PMID 40051702, 2025).
keratoconus (2 papers, 2016). A degenerative, structural disorder of the eye, characterized by a cone-shaped protrusion of the cornea. "Albeit, recent studies have shown that matrix metalloproteinases MMP1 and 9, AZGP1, SFRP1, IGKC and cell adhesion molecules ICAM-1 and VCAM-1 to be specifically regulated in keratoconus, indicating their probable exclusive role in keratoconus." (PMID 27493978, 2016). "A presumed progression risk factor of keratoconus is the contact lens wear, especially rigid gas permeable contact lenses that induce the upregulation of IL-6, TNF-alpha, ICAM-1, and VCAM-1 in the tears of subjects with keratoconus." (PMID 27563164, 2016).
kidney stone (2 papers, 2015 to 2025). "Concurrently, six protein ratio pairs were found to inhibit kidney stone occurrence: GGT1/MME protein level ratio, ACE2/MME protein level ratio, ITIH3/VCAM1 protein level ratio, GZMA/TNFRSF8 protein level ratio, CRADD/HSPA1A protein level ratio and GZMA/TNFRSF4 protein level ratio." (PMID 40673688, 2025).
leukocytosis (2 papers, 2022 to 2025). "This was associated with leukocytosis, particularly monocytosis, and elevated VCAM-1 expression in coronary arteries and despite much lower plasma cholesterol levels in SR-B1 KO mice." (PMID 36714321, 2022). "In parallel, adhesion-axis interventions informed by leukocytosis biology (e.g., ICAM-1/LFA-1, α4-integrin/VCAM-1) reduce leukocyte transmigration and BRB breakdown in vivo, supporting trafficking-based barrier protection in inflammatory retinopathies." (PMID 41394857, 2025).
Lymphadenopathy (2 papers, 2016 to 2022). Enlargement (swelling) of a lymph node. "Another important issue that merits comment is a higher circulating VCAM-1 in sarcoidosis patients with extrapulmonary lymphadenopathy." (PMID 36494464, 2022). "In patients having lymphadenopathy, CLL cells are able of collecting prosurvival signals through αLβ2 and α4β1 integrins linked to ICAM-1 and VCAM-1 mediated diapedesis." (PMID 27374180, 2016).
macular edema (2 papers, 2022 to 2023). "Taken together, our results suggest that nAMD patients had significantly higher intraocular levels of VCAM-1, ICAM-1, CD44 and CD62L and that higher level of VCAM-1 is related to macular fibrosis and increased central retinal thickness (a sign of macular oedema)." (PMID 37985993, 2023).
medulloblastoma (2 papers, 2020 to 2022). A malignant, invasive embryonal neoplasm arising from the cerebellum. "Moreover, for both metastasis and medulloblastoma models, significantly greater histologic VCAM-1 staining intensity was evident in regions of MRI-visible hypointensities than in regions without hypointensities (Kruskal–Wallis and post hoc Dunn test, P < 0.001 for both)." (PMID 35312755, 2022). "We found that among the selected genes, three of the downregulated genes (BOC, VCAM1, and TP63) followed the same pattern as ERBB4 and showed a higher expression in Group 4 medulloblastomas." (PMID 32316671, 2020). "Finally, we correlated their expression with patient outcome finding that altered VCAM1, TP63, ANKRD1, THBS1, and PTHLH levels correlated with lower patient survival in Group 4 medulloblastoma samples." (PMID 32316671, 2020). "Next, we moved our attention to genes already related to medulloblastoma based on the literature and validated some of them, such as POSTN, BOC, VCAM1, and TP63 among the downregulated genes and ANKRD1, THBS1, NRG1, PTHLH, and HBEGF among the upregulated ones in DAOY and D283Med cells." (PMID 32316671, 2020). "Next, we wanted to assess the sensitivity of VCAM-1–targeted MPIO (VCAM-MPIO) in conjunction with T2*-weighted MRI for detection of the tumor-brain interface compared with conventional MRI, and further extend this analysis to a xenograft model of medulloblastoma to assess its broader applicability." (PMID 35312755, 2022).
membranous nephropathy (2 papers, 2012 to 2024). "Additionally, the expression levels and predictive performance of VCAM1 in other renal diseases commonly associated with DN, such as membranous nephropathy, need to be evaluated." (PMID 39319258, 2024). "In addition, the clinical utility of using urine VCAM-1 to track disease progression in ANCA-GN, FSGS and membranous nephropathy should also be carefully examined in future studies." (PMID 22788914, 2012). "Interestingly, the urinary levels of VCAM-1 in patients with ANCA-GN, FSGS and membranous nephropathy were not statistically different from the urine levels of VCAM-1 in patients with active LN." (PMID 22788914, 2012).
meningoencephalitis (2 papers, 2014 to 2024). Inflammation of the meninges and brain, generally secondary to an infectious cause. "In addition, the role of the VLA-4/VCAM-1 pathway in the establishment of meningoencephalitis induced by T. cruzi has been suggested." (PMID 25010691, 2014). "Furthermore, a study described an increased expression of VCAM-1 in blood vessels surrounded by VLA-4+ inflammatory cells, leading to meningoencephalitis during the acute phase of experimental CD." (PMID 38785783, 2024).
microcephaly (2 papers, 2015 to 2026). A congenital or acquired developmental disorder in which the circumference of the head is smaller than normal for the person's age and sex. "In three models, newborns with hyperEPO alone (IL-6R, VCAM-1, VEGF-R1, yellow) were at significantly greater risk of microcephaly than referent children." (PMID 25793991, 2015).
nasopharyngeal carcinoma (2 papers, 1999 to 2021). A carcinoma arising from the nasopharyngeal epithelium. "The concentration of circulating ICAM-1, E-selectin and VCAM-1 was significantly increased in nasopharyngeal carcinoma." (PMID 9888481, 1999).
neovascular age-related macular degeneration (2 papers, 2023 to 2025). "Recently, increased VCAM1 expression was found to potentially contribute to the development of macular fibrosis in neovascular age-related macular degeneration patients." (PMID 39990328, 2025).
ocular hypertension (2 papers, 2022 to 2025). Abnormally high intraocular pressure. "Thus, further investigations on the role of VCAM1 will help better understand the role of cell adhesion proteins and the pathogenesis of ocular hypertension and POAG." (PMID 36176278, 2022).
oral cancer (2 papers, 1999 to 2019). "Correspondingly, VCAM-1 and E-selectin were significantly increased in laryngeal carcinoma, whereas only E-selectin was elevated in oral carcinoma." (PMID 9888481, 1999). "TNF-α upregulated the expression of VCAM-1 in vascular endothelium, which is a ligand of very late activation antigen 4 (VLA-4) on cancer cells, and finally enhanced the adhesion and fusion between oral cancer cells and vascular endothelial cells through the VCAM-1/VLA-4 pathway." (PMID 31380426, 2019).
oral squamous cell carcinoma (2 papers, 2016 to 2022). "For instance, Song and colleagues demonstrated that TNF-α could enhance oral squamous cell carcinoma (OSCC) × HUVEC fusion through the α4β1 (very late antigen-4 (VLA-4))/vascular cell adhesion molecule-1 (VCAM-1) pathway." (PMID 36555709, 2022).
papillary renal cell carcinoma (2 papers, 2016 to 2022). A rare subtype of renal cell carcinoma, arising from the renal tubular epithelium and showing a papillary growth pattern, which typically manifests with hematuria, flank pain, palpable abdominal mass or nonspecific symptoms, such as fatigue, weight loss or fever. "CD106 (VCAM1) protein expression tended to be lower in healthy renal tubules compared to renal adenocarcinoma." (PMID 36221114, 2022).
Papillary Thyroid Carcinoma (2 papers, 2016 to 2024). "Further, in a BRAF-mutated papillary thyroid cancer cell line (BCPAP), vemurafenib, an inhibitor of mutant BRAF activity, was shown to upregulate VCAM-1 expression, which was reduced by the administration of the Akt inhibitor MK2206." (PMID 39768198, 2024). "Circulating levels of TNF-α and the adhesion molecules L-Selectin and VCAM-1 as well as their expression in the primary tumors of patients with benign thyroid diseases and papillary thyroid carcinoma (PTC) have been determined in this study." (PMID 26881177, 2016).
parasite infection (2 papers, 2019 to 2022). "We compared expression of ICAM1, ICAM2, and VCAM1 proteins in the vasculature of the brain at the first peak of parasitemia in both strains, by ex-vivo microscopy." (PMID 35787830, 2022). "Finally, ICAM-1 and VCAM-1 expression were not modulated by the parasite infection." (PMID 31068227, 2019).
plaque psoriasis (2 papers, 2020 to 2023). "It has previously been reported that ADA treatment decreased serum levels of vascular cell adhesion molecule 1, a biomarker of cardiovascular diseases, in patients with plaque psoriasis, indicating the cardioprotective effects of ADA." (PMID 36902720, 2023).
Pleural effusion (2 papers, 1996 to 2013). The presence of an excessive amount of fluid in the pleural cavity. "In pleural fluid, levels of s.VCAM-1 and s.ICAM-1 were increased in pleural effusions." (PMID 18475740, 1996). "Up-regulation of s.VCAM-1 and s.ICAM-1 in serum, along with increased levels of sE-selectin in pleural effusions from tuberculous patients, may result in transmigration of activated inflammatory cells inducing pleural damage, which may contribute to the pathological processes involved." (PMID 18475740, 1996). "Additionally, PMCs derived from transudative pleural effusion expressed lower levels of ICAM-1 and VCAM-1 than TPE derived-PMCs, though it was not statistically significant." (PMID 24069325, 2013).
postmenopausal osteoporosis (2 papers, 2018 to 2021). Metabolic disorder associated with fractures of the femoral neck, vertebrae, and distal forearm. "In this study, in a rat ovariectomy- (OVX-) induced postmenopausal osteoporosis model, aberrant expression of a microRNA miR-142-5p and vascular cell adhesion molecule 1 (VCAM-1) was found by RNA sequencing analysis and qRT-PCR." (PMID 29789783, 2018). "Garlic tablets not only have a good effect on postmenopausal osteoporosis but also have many beneficial effects on oxidative stress, and can reduce the activity of NADPH oxidase and the expression of vascular cell adhesion molecule 1 (VCAM-1), thereby reducing inflammation." (PMID 34366840, 2021).
progeria (2 papers, 2020 to 2025). "Finally, the progeria-derived endothelial cells produced vascular cell adhesion protein 1 (VCAM1) and E-selectin proteins, while healthy-derived cells did not." (PMID 32842478, 2020). "Previous studies have shown that vascular cell adhesion molecule 1 (VCAM1), a vascular inflammation marker, expression is elevated in progeria mice and tissue‐engineered blood vessels (viTEBVs)." (PMID 39422121, 2025).
retinal haemorrhages (2 papers, 2020 to 2026). "CM-retinopathy is a constellation of ocular changes that includes retinal whitening, retinal haemorrhages, vascular changes and papilledema, and increased expression of vascular cell adhesion molecule-1 (VCAM-1)." (PMID 32703204, 2020).
Right ventricular hypertrophy (2 papers, 2024 to 2026). In this case the right ventricle is more muscular than normal, causing a characteristic boot-shaped (coeur-en-sabot) appearance as seen on anterior- posterior chest x-rays. "In vivo, adenoviral MALAT1 overexpression attenuated PH, right ventricular hypertrophy (RVH), vascular remodeling, and reduced ET-1 and VCAM1 expression in SS mice." (PMID 41597229, 2026).
SARS-CoV infection (2 papers, 2021 to 2024). "Differences in sequelae symptoms, cardiovascular biomarkers (VCAM-1, ICAM-1, and ACE2), Severe Acute Respiratory Syndrome Coronavirus 2 neutralization antibodies (SARS-CoV-2 nAb) and cytokines (IFN-γ, IL-6, and IL-17) were analyzed between the two groups." (PMID 39669584, 2024).
scrub typhus (2 papers, 2021 to 2024). Scrub typhus is a rare dust mite-borne infectious disease caused by the Orientia tsutsugamushi bacterium and characterized clinically by an eruptive fever which is potentially serious. "Herein we show that DKK-1 was negatively correlated with both markers of immune activation (i.e. sCD163 and sCD14) and vascular inflammation (i.e. VCAM1) in patients with scrub typhus and infectious controls suggesting a common mechanism." (PMID 33914733, 2021).
septic shock (2 papers, 2022 to 2025). Shock caused by infection; frequently caused by gram negative bacteria, although some cases have been caused by other bacteria, viruses, fungi, and protozoa; characterized by fever, chills, tachycardia, tachypnea, and hypotension. "Within the septic shock group, there was a positive correlation between VCAM-1 and Charlson comorbidity score at 1 and 3 month follow-up, and at the 6-month follow-up timepoint, IL-6 was positively correlated with age and negatively correlated with EQ-5D-5L VAS score." (PMID 41180006, 2025).
status epilepticus (2 papers, 2019 to 2023). Status epilepticus is defined as a continuous seizure lasting more than 30 min, or two or more seizures without full recovery of consciousness between any of them. "In a pilocarpine epilepsy model, status epilepticus promoted leukocyte 4 integrin-mediated leukocyte adhesion to vascular cell adhesion molecule-1, whereas antibodies against leukocyte 4 integrin can prevent seizure development and status epilepticus." (PMID 37470000, 2023). "Furthermore, our previous research has shown that α4 integrins can mediate neutrophil rolling in the inflamed brain microcirculation following status epilepticus, suggesting the interaction between VLA4 and VCAM-1 may is also act as a neutrophil recruitment pathway during sterile brain inflammation." (PMID 31427644, 2019).
systemic inflammatory response syndrome (2 papers, 2015 to 2024). SIRS is a serious condition related to systemic inflammation, organ dysfunction, and organ failure. "In contrast, VCAM-1 was no longer independently associated with mortality after adjusting for inflammation in critically ill patients with systemic inflammatory response syndrome." (PMID 39409009, 2024).
thyroid (2 papers, 2016 to 2020). "Cytoplasmic immunoreactivity of VCAM-1 was observed in patients with thyroid diseases." (PMID 26881177, 2016). "However, four genetic variants associated with thyroid phenotypes published in the GWAS catalog (rs3761959, rs7528684, rs505922, and rs3184504) were also associated in cis and trans with nine circulating protein abundances (BGAT, CHSTB, DC-SIGN, Desmoglein-2, DYR, FCRL3, GP1BA, MBL, and VCAM-1)." (PMID 32182948, 2020).
thyroid cancer (2 papers, 2015 to 2016). "In thyroid carcinoma also, there might be shedding of VCAM-1 from the thyroid cancer cells into circulation which may be the factor accounting for the significantly elevated serum levels of VCAM-1." (PMID 26881177, 2016). "Although not significant, the incidence of VCAM-1 expression was higher in the thyroid cancer patients as compared to the patients with benign thyroid diseases." (PMID 26881177, 2016).
Ureteral obstruction (2 papers, 2011 to 2023). Obstruction of the flow of urine through the ureter. "VCAM1 expression was markedly elevated in a fibrotic model of unilateral ureteral obstruction." (PMID 37266443, 2023).
venous thromboembolism (2 papers, 2023 to 2024). Occlusion of the lumen of a vein by a thrombus that has migrated from a distal site via the blood stream. "Circulating levels of VCAM1 were also elevated in patients with venous thromboembolism, indicating not only exacerbated endothelial activation and dysfunction but also the favorable interaction of neutrophil adhesion molecules with their endothelial ligands for neutrophil migration." (PMID 38919521, 2024).
vivax malaria (2 papers, 2013 to 2015). "Our findings of increased endothelial activation in severe vivax malaria are consistent with a recent study reporting higher concentrations of ICAM-1 and VCAM-1 in severe compared to uncomplicated vivax malaria." (PMID 25569250, 2015). "It was observed that TNF-α, IL-10, ICAM-1 and VCAM-1 were the 4 best individual predictors of complicated vivax malaria with AUROC of 0.89 (95% CI: 0.84 - 0.94), 0.79 (95%CI: 0.73- to 0.86), 0.63 (0.55-0.71) and 0.84 (95% CI: 0.78- 0.90) respectively." (PMID 24324686, 2013).
Acidosis (1 paper, 2022). Abnormal acid accumulation or depletion of base. "While angiopoietin 2 (Angpt-2) and P-selectin were associated with TFF3, I-FABP was correlated with soluble Fms-related receptor tyrosine kinase 1 (sFlt-1) as well as soluble vascular cell adhesion molecule 1 (sVCAM-1) in children with acidosis." (PMID 36069443, 2022).
acute chest syndrome (1 paper, 2018). A vaso-occlusive crisis of the pulmonary vasculature occurring in patients with sickle cell disease. "Several other studies have reported that levels of VCAM-1 are particularly increased in severe complications of SCD, including HbSS vaso-occlusive crises and acute chest syndrome, and thus, may serve as a promising biomarker of disease severity and associated complications of SCD." (PMID 30577523, 2018).
acute leukemia (1 paper, 2018). A clonal (malignant) hematopoietic disorder with an acute onset, affecting the bone marrow and the peripheral blood. "In immunohistochemistry studies, VCAM-1 overexpression was found in biopsy material from acute leukemias." (PMID 30534565, 2018).
acute promyelocytic leukemia (1 paper, 2020). An aggressive form of acute myeloid leukemia (AML), characterized by arrest of leukocyte differentiation at the promyelocyte stage, due to a specific chromosomal translocation t(15;17) in myeloid cells. "In addition, heparin reduced acute promyelocytic leukemia cell line NB4 adhesion to the immortalized human microvascular endothelial cell line-1 (HMEC-1), and the expression of intercellular adhesion molecule 1 (ICAM-1) and vascular cell adhesion molecule 1 (VCAM-1) on HMEC-1 cells." (PMID 32754595, 2020).
AIDS (1 paper, 2020). A syndrome resulting from the acquired deficiency of cellular immunity caused by the human immunodeficiency virus (HIV). "The correlation between viro-immunological state of AIDS and the plasma biomarkers of endothelial injury such as Intracellular Adhesion Molecule 1 (ICAM-1), Vascular Cell Adhesion Molecule 1 (VCAM-1), and E-selectin are well-established." (PMID 32660065, 2020).
alcohol- (1 paper, 2020). "ACT and Sil failed to affect the hepatic levels of TPO, RBP4, IL-23, ICAM-1, NGAL, and VCAM-1 in acute alcohol-injured mice compared with the model group." (PMID 32719658, 2020).